RNU2-28P (RNA, U2 small nuclear 28, pseudogene)
Gene: Small nuclear RNA gene on chromosome 3 (81,509,476 to 81,509,664, forward strand). Ensembl gene ENSG00000222389.
Homologues: Orthologues: chimpanzee U2 (75% identical), dog U2 (40% identical), guinea pig U2 (36% identical), pig U2 (35% identical), rat LOC120097278 (35% identical), rabbit U2 (33% identical), dog U2 (32% identical), pig U2 (31% identical). Paralogues in human: RNU2-2 (46% identical), U2 (46% identical), RNU2-48P (45% identical), RNU2-36P (44% identical), RNU2-59P (44% identical), RNU2-61P (44% identical), RNU2-62P (44% identical), RNU2-63P (44% identical), RNU2-6P (44% identical), RNU2-23P (44% identical), RNU2-26P (44% identical), RNU2-32P (44% identical), and 65 more.